PHGDH (phosphoglycerate dehydrogenase)
Diseases named in the same sentence as PHGDH in open-access papers (continued):
Sharing a sentence is not in itself a finding about the gene and the disease.
breast carcinoma (continued). "Hypoxia has been shown to induce expression of PHGDH, PSAT1 and PSPH in breast cancer cells and PHGDH has been shown to be overexpressed in various cancer types, including colorectal, non-small cell lung, cervical and breast cancers." (PMID 36226069, 2022). "Very similar data were observed when analyzing the brain metastasis of a patient affected by breast cancer, a detail of particular interest because breast cancer and melanoma cells overexpress some genes of the SSP, as PHGDH, amplified at the genomic level in a specific ER-negative tumor subset." (PMID 34207731, 2021). "PHGDH, the initial enzyme in the SSP, is reportedly upregulated in breast cancers and melanomas." (PMID 34822010, 2021). "All osteosarcoma cell lines were found to have PHGDH levels that were significantly higher than those of mesenchymal cells or the known-negative breast-cancer cell line." (PMID 33503424, 2021). "Despite in vitro cytotoxicity of PHGDH inhibition, the enzyme silencing using inducible shRNA system in fully established breast cancer xenografts did not delay tumor growth when compared to the xenografts with unaltered PHGDH expression." (PMID 32138178, 2020). "Immunoblotting analyses revealed that PHGDH was markedly increased in BC cells compared with breast cancer cells (MCF7 and MDAMB231), which were used as negative control as shown in the previous study." (PMID 32386122, 2020). "Evaluating the same assay on non-TNBC revealed four genes: ERBB2, ESR1, PHGDH, and TYMS containing both germline and somatic mutations significantly associated with that type of breast cancer." (PMID 32724790, 2020). "This explains why the inhibitory effect of PHGDH suppression on breast cancer cell proliferation is unlikely to be rescued by the supplemented extracellular serine." (PMID 32296646, 2020). "Indeed, phosphoglycerate dehydrogenase (PHGDH), the first enzyme of the pathway, is amplified in breast cancer and melanoma, where it functions as an oncogene and the SBP is also the target of a series of oncogenes." (PMID 32783398, 2020). "Surprisingly, chemical/genetic disruption of SBP did not delay BL and breast cancer xenografts growth, suggesting the existence of mechanisms compensating the PHGDH/PSAT1 absence in vivo." (PMID 32138178, 2020). "Elevated protein expression of PHGDH are found in 21% of melanoma samples, 70% of estrogen receptor (ER)-negative and triple-negative breast cancers." (PMID 30744688, 2019). "PHGDH protein level is elevated in 70% of estrogen receptor (ER)-negative breast cancers and suppression of PHGDH in breast cancer cell lines decreases cell proliferation and reduces serine synthesis." (PMID 30857125, 2019). "Of note, a decrease in PHGDH expression reduced proliferation not only in melanoma cells but also in breast cancer cells, and heterologous overexpression in non-transformed cells predisposes cells to transformation." (PMID 29674683, 2018). "Recently, human PHGDH was also shown to be able to reduce α-ketoglutarate, a structural analogue of PHP, to 2-hydroxyglutarate (2-HG), both in vitro and in the PHGDH-amplified breast cancer cell line MDA-MB-468." (PMID 29262655, 2017). "In addition, the amplification of phosphoglycerate dehydrogenase (PHGDH), the first enzyme of the SSP and catalyze the conversion of 3-PG to 3-phosphohydroxypyruvate (3-PH), also occurs in some breast cancers." (PMID 28931725, 2017). "What is even more interesting is that in non-tumorigenic breast cancer cells, overexpression of PHGDH alone lead to disruption of the acinar cellular morphology and predisposed them to neoplastic transformation, making the PHGDH a bona fide oncogene." (PMID 29312889, 2017). "In 7 out of 17 breast cancer datasets high PHGDH expression represented a negative prognostic factor, predicting negative patient survival." (PMID 25436979, 2014). "TMA showed that the TNBC-type breast cancer tissues highly expressed PHGDH, PSPH, and SHMT1, but not the luminal-A-type tissues (p<0.001)." (PMID 24979213, 2014).
breast carcinoma (continued). "In primary breast tumors, PHGDH localizes to a genomic region of recurrent copy number gain and its protein levels are elevated in 70% of estrogen receptor (ER)-negative breast cancers." (PMID 24318446, 2013). "RNAi-mediated depletion of PHGDH has little effect on the viability of untransformed breast epithelial cells or breast cancer cells without PHGDH amplification/overexpression." (PMID 23229761, 2013). "Notably, PHGDH knockdown had no impact on the proliferation of estrogen and progesterone receptor-positive breast cancer cells." (PMID 38945960, 2024). "However, PHGDH knockdown does not affect tumor growth in a different breast cancer model, arguing that SSP activity is only required in some contexts." (PMID 37187454, 2023). "However, a regulatory mechanism that activates PHGDH in breast cancer cells has not been identified yet." (PMID 35122791, 2022). "We examined whether the ability of basal breast cancer cells to proliferate without exogenous S/G is reliant on serine biosynthesis by treating basal HCC1806 cells with the PHGDH inhibitor PH-755 while growing with and without S/G." (PMID 35045283, 2022). "Indeed, PHGDH expression has no impact on the progression of breast cancer implanted in pancreas—a serine-rich environment-, while tumor growth increases when cells are injected in mammary fat pads—a serine-low environment." (PMID 33499022, 2021). "Significantly reduced breast cancer cell proliferation was observed upon treatment with NCT502, a recently described inhibitor of the SBP, in four out of the eight cell lines tested (ZR‐75‐1, T47D, MDA‐MB‐468 and HCC1143), while its PHGDH inactive form only had an effect in T47D cells (Fig EV5A)." (PMID 32783398, 2020). "Four breast cancer datasets shared both enzymes, PHGDH and SHMT2, as negative prognostic factors." (PMID 30857125, 2019). "When considering PHGDH prognostic significance in a broad context, bioinformatic analysis of human breast and lung cancer mRNA data sets found high PHGDH expression to be a negative prognostic marker in breast cancer patients in seven out of 17 breast cancer datasets." (PMID 30857125, 2019). "In contrast to previous observations, however, we found that Hs578T, a breast cancer cell line with relatively high PHGDH protein expression levels, but without a genomic amplification of PHGDH, was insensitive to PHGDH knockdown, as was the non-amplified and low-expressing MDA-MB-231." (PMID 29568346, 2018). "Consistent with this notion, PHGDH knockdown abrogates breast cancer stem cell survival under hypoxia, without impairing cancer cell proliferation, and increases oxygen consumption rate and extracellular acidification rate as a consequence of reduced glucose shunting to the serine synthesis pathway." (PMID 28649560, 2017). "Most, but not all, ER− breast cancer cells show high-level expression of PHGDH." (PMID 24318446, 2013). "However, PHGDH knockdown does not affect the growth of three of these models when assessed as fully established breast cancer xenografts in mice." (PMID 24318446, 2013). "It was also found that the silencing of PHGDH under hypoxia conditions could lead to the decrease of NADPH level, disturb mitochondrial redox homeostasis, and promote apoptosis, resulting in the abrogation of breast cancer stem cells enrichment and lung metastases formation." (PMID 36998464, 2023). "Therefore, it is possible that curcumin, in addition to inhibiting PHGDH directly by binding to its NAD+ pocket, hinders its activity indirectly by down-regulating expression of NAMPT (also known as visfatin) as has been demonstrated in breast cancer cell lines (MDA-MB-231, MDA-MB-468, and MCF-7)." (PMID 30857125, 2019).
breast carcinoma (continued). "However, this was somewhere neglected until the recent discovery that the first enzyme of SSP, phosphoglycerate dehydrogenase (PHGDH), is genetically amplified in breast cancer and melanoma, and overexpression of the SSP components are correlated with poorer prognosis in breast cancer patients." (PMID 29312889, 2017). "However, PHGDH knockdown does not affect tumor maintenance and growth in established breast cancer xenograft models, suggesting that PHGDH-dependent cancer cell growth may be context-dependent." (PMID 24318446, 2013). "While in breast cancer cells MDA-MB-231, there is no amplification of PHGDH, the highly consumed glucose is diverted into alanine but not serine or glycine synthesis." (PMID 30744688, 2019). "In addition, PHGDH suppression inhibited the growth of mammary tumours in mice, although the suppressive effect seemed to depend on the tumour stage, as a similar in vivo study in more established mammary tumours reported no significant reduction in tumour growth following PHGDH knockdown." (PMID 29568346, 2018). "Using data from the Cancer Cell Line Encyclopedia (CCLE) and our own qPCR and western blots, we found that breast cancer cell lines robustly maintain the low-PSAT1 phenotype of luminal tumors, while the differences in PHGDH and PSPH were less pronounced or absent." (PMID 35045283, 2022). "Importantly, in the explanted tumors with PSAT1 or PHGDH knockdown, there was no re-expression of the enzymes, indicating that disruption of SBP in the breast cancer cell model is not sufficient to delay the growth of an established tumor." (PMID 32138178, 2020).
melanoma (94 papers, 2012 to 2026). A malignant, usually aggressive tumor composed of atypical, neoplastic melanocytes. "A high PHGDH expression has been extensively reported in several tumors, particularly breast and melanoma, and its high expression in these tumors is associated with poor prognosis." (PMID 36793607, 2023). "Melanoma cells harbor an amplified gene that encodes phosphoglycerate dehydrogenase (PHGDH), the first enzyme in the serine biosynthetic pathway and moreover one of the few acknowledged metabolic oncogenes." (PMID 32509589, 2020). "In an NRAS mutation model of melanoma, PHGDH was found to be upregulated." (PMID 33511334, 2020). "Serine/glycine deprivation activates a multi-transcription factor response involving ATF4, FOXC1, and cooperation between BRAFV600E and ATF4 in melanoma to induce PHGDH expression." (PMID 41486146, 2026). "Functional indispensability is underscored by tumor suppression upon PHGDH ablation in melanoma and AML." (PMID 41486146, 2026). "In addition, it was found that the PHGDH gene, encoding the rate-limiting enzyme of the serine synthesis pathway, is frequently amplified in melanoma cells, suggesting that serine metabolic reprogramming is crucial for the progression and drug resistance of melanoma." (PMID 40004003, 2025). "Elevated levels of PHGDH expression have been observed in various solid tumors, including triple-negative breast cancer, melanoma, and lung adenocarcinoma, and inhibiting this enzyme has demonstrated the ability to impede cancer cell proliferation." (PMID 38690164, 2024). "Phosphoglycerate dehydrogenase (PHGDH) catalyzes the first step of the serine/glycine pathway and is overexpressed in melanoma cell lines and tumors." (PMID 38339003, 2024). "Two key metabolic genes, PKM2 and PHGDH, are upregulated in melanoma TILs compared to healthy pCD8s." (PMID 38023136, 2023). "PHGDH (d-3-phosphoglycerate dehydrogenase) is overexpressed in multiple cancers, correlates with tumor growth, and has been shown to be increased in 40% of melanoma samples." (PMID 38023136, 2023). "The upregulation of serine through dietary serine supplementation or gene overexpression of 3-phosphoglycerate dehydrogenase (PHGDH), the rate-limiting enzyme in serine synthesis, effectively promotes melanoma development." (PMID 36003368, 2022). "In BRAF inhibitor-resistant melanoma cells, expression of the serine biosynthetic enzymes PHGDH, PSAT1, and PSPH is enhanced to support folate cycle metabolism, and depletion of PHGDH sensitizes resistant cells to BRAF inhibitors." (PMID 35011702, 2022). "The amplification of breast and melanoma cancers has an upregulation of 3-phosphoglycerate dehydrogenase (PHGDH), a rate-limiting serine biosynthesis enzyme that was found to be required for growth in vitro and in vivo models." (PMID 36295863, 2022). "Targeting PHGDH, which catalyzes the rate-limiting step of glucose-derived serine synthesis, is promising in restraining melanoma brain metastasis." (PMID 36003368, 2022). "Some human melanoma and breast tumors require PHGDH for development in vitro, which is why high levels of PHGDH have been reported." (PMID 36358687, 2022). "In human NRAS-mutant melanoma xenograft models, upregulation of serine biosynthesis and expression of PHGDH are responsible for the resistance to MAPK kinase inhibitors." (PMID 35011702, 2022). "Here, phosphoglycerate dehydrogenase (PHGDH) was selected for further analysis because it was a key mediator involved in the suppression of apoptotic response in melanoma cells." (PMID 33732415, 2021).
melanoma (continued). "Consistent with this, increased PHGDH copy number is a feature of triple-negative breast cancers and melanomas, whilst brain metastases demonstrate particularly high levels of expression of PHGDH and other SGOC enzymes." (PMID 34637000, 2021). "If melanoma cell cultures are supplemented with exogenous serine, cellular proliferation continues to stay reduced in PHGDH silenced cells." (PMID 32509589, 2020). "It was shown that upregulated level of PHGDH is important for tumor initiation and promotion in melanoma mouse model TyrCreER: BRAFV600E; PHGDHtetO in cooperation with BRAFV600E mutation." (PMID 33091721, 2020). "Authors performed genetic studies to show that the PHGDH gene is amplified in 16% of all cancer types and 40% in melanoma." (PMID 33091721, 2020). "PHGDH silencing in melanoma cell lines with increased PHGDH copy number leads to the signficant growth inhibition." (PMID 33091721, 2020). "PHGDH gene copy number gain is observed at a higher frequency in melanoma than other cancers 4, 33 and PHGDH expression can accelerate melanoma progression in mice." (PMID 32226297, 2020). "Given the high frequency of PHGDH gene copy number gain observed in melanoma compared to other cancers, we sought to examine the effect of PHGDH expression on melanocyte biology." (PMID 31331318, 2019). "Copy number gain of the D-3-phosphoglycerate dehydrogenase (PHGDH) gene, which encodes the first enzyme in serine biosynthesis, is found in some human cancers including a subset of melanomas." (PMID 31331318, 2019). "Because PHGDH gene copy number gain is observed with higher frequency in melanoma compared to other cancers and PHGDH expression can accelerate melanoma progression in mice, the effect of PHGDH expression on melanocyte biology is of particular interest." (PMID 31331318, 2019). "Supporting this notion, PHGDH gene expression is up-regulated in diverse cancer cells, such as esophageal adenocarcinoma, triple-negative breast cancer, and melanoma." (PMID 26356530, 2015). "The expression of PHGDH has been found upregulated (amplification of chromosome 1p12) in triple negative breast cancer and in melanoma, suggesting that tumors containing amplification of PHGDH take advantage from serine biosynthesis activity." (PMID 25436979, 2014). "The same study found that PHGDH is recurrently amplified in a genomic region of a focal copy number gain most commonly found in melanoma." (PMID 24743024, 2014). "Previous studies in 150 human melanoma samples showed that 39% of the samples exhibited PHGDH copy number gain and high protein expression." (PMID 24733054, 2014). "PHGDH is recurrently amplified in a genomic region of focal copy number gain in melanoma based on an analysis of human cancers." (PMID 24138801, 2013). "Melanoma, however, with 39 % of samples exhibiting some form of copy number gain, had the highest frequency of PHGDH amplification among tumor types that were analyzed." (PMID 23229761, 2013). "One study has shown that targeting PHGDH resensitizes resistant melanoma to MAPK inhibition." (PMID 38339003, 2024). "Interestingly, PHGDH has previously been proposed as a therapeutic target for melanoma in overcoming resistance to MEKis PD0325901 and trametinib, where suppression of PHGDH led to sensitivity in MEKi-resistant melanoma cells." (PMID 38730673, 2024). "The upregulation of the rate-limiting enzyme of serine biosynthesis, 3-phosphoglycerate dehydrogenase (PHGDH), has been identified in a large subset of cancers, including melanoma, Ewing’s sarcoma, breast, colorectal, pancreatic, and non-small cell lung cancers." (PMID 33503424, 2021).